INS (insulin)
Diseases named in the same sentence as INS in open-access papers (continued):
Sharing a sentence is not in itself a finding about the gene and the disease.
type 2 diabetes (continued). "The mechanisms underlying the relation between type 2 diabetes and breast cancer risk may be related to alterations in circulating concentrations of insulin and insulin-like growth factors (IGFs)." (PMID 20184722, 2010). "The observed increase of serum IGF-1 and insulin-to-glucose ratio indicates that sleep restriction may result in an increased risk to develop type 2 diabetes." (PMID 20414467, 2010). "Enhancing insulin secretion through a glucose dependent mechanism has been considered an attractive therapeutic approach since it can restore the defective physiological pathway in type 2 diabetes patients and minimize the risk of hypoglycaemia." (PMID 22615610, 2010). "Beyond the effect of activity on body mass and composition, physical activity may reduce the risk for type 2 diabetes directly through improvements in insulin sensitivity." (PMID 20041024, 2009). "The massive obesity of Nscl-2 mutant mice and the insulin resistance of Nscl-2 deficient adipocytes suggested that Nscl-2 mutants might suffer from type II diabetes." (PMID 19436734, 2009). "Among these, a relatively common polymorphism of PPARγ, Pro12Ala of PPARγ2, the isoform expressed only in adipose tissue has been shown to be associated with lower body mass index, enhanced insulin sensitivity, and resistance to the risk of type 2 diabetes in human subjects carrying this mutation." (PMID 19390629, 2009). "The major C-risk allele of rs4607103 near ADAMTS9, conferring increased risk of type 2 diabetes, associated with increased fasting plasma glucose levels (p = 0.007) and a reduced insulin-stimulated glucose uptake during a euglycemic-hyperinsulinemic clamp (p = 0.002)." (PMID 19789630, 2009). "However, this does not change the overall finding and conclusion that genes involved in insulin signaling are upregulated in people at risk of – and prior to - type 2 diabetes development, and subsequently are downregulated in the diabetic state." (PMID 19668377, 2009). "Thus, genetic variation in type 2 diabetes risk genes is supposed to affect insulin sensitivity and/or β-cell function." (PMID 18714373, 2008). "However, a high percentage of young African American girls are overweight, have reduced insulin sensitivity, have at least 1 risk factor for metabolic syndrome, and have type 2 diabetes." (PMID 18793503, 2008). "We hypothesized that common polymorphisms in the ARNT gene might increase the susceptibility to type 2 diabetes through impaired glucose-stimulated insulin secretion." (PMID 18366646, 2008). "Because NO not only inhibits insulin release but also stimulates glucagon release this observation thus underlined a possible pathogenic role of the islet NO system in the development of type 2 diabetes." (PMID 18478125, 2008). "This condition is a feature of variousdisorders, such as type 2 diabetes, which may range from predominantly insulinresistance with relative insulin deficiency to a predominatly secretory defectof insulin." (PMID 18604303, 2008). "Type 2 diabetes is caused by defects in both insulin signaling and insulin secretion." (PMID 19007436, 2008). "To test this hypothesis we searched for indirect evidence that SNPs marking common haplotypes were associated with type 2 diabetes or altered insulin secretion." (PMID 18366646, 2008). "Due to the natural history of type 2 diabetes, many patients eventually progress to a level of insulin deficiency that requires initiation of prandial insulin (or pharmacotherapy targeted to prandial insulin control) in addition to basal insulin." (PMID 17448241, 2007). "However, as the disease progresses, the capacity of patients with type 2 diabetes to respond to PPG excursions becomes progressively impaired due to reduced endogenous insulin secretion resulting from loss of β-cell function." (PMID 17448241, 2007). "Interestingly, EIF4A2 has also been linked to type-2 diabetes and in rat cells appears to suppress insulin expression." (PMID 17244347, 2007).
type 2 diabetes (continued). "We tested the hypotheses that these previously identified variants were associated with type 2 diabetes in African Americans ascertained in Arkansas and that they altered insulin secretion in glucose tolerant African American subjects." (PMID 16869959, 2006). "However, hyperinsulinaemia per se seems unlikely as a mediator of low adiponectin levels, since adiponectin levels remain low in the later stage of type 2 diabetes in association with decreased insulin levels." (PMID 16669997, 2006). "Insulin treatment in type 2 diabetes patients usually leads to weight increase which may cause further injury to the kidney." (PMID 16774676, 2006). "The increased concentrations of TNF-α and IL-6, associated with obesity and type 2 diabetes, might interfere with insulin action by suppressing insulin signal transduction, which in turn might promote inflammation." (PMID 15904534, 2005). "The pathophysiology of type 2 diabetes involves, in part, a “relative” deficiency of insulin." (PMID 15736996, 2005). "However, the impact of daily life stress on glucose levels in insulin-resistant individuals, who are at risk of type 2 diabetes, remains unclear." (PMID 41076451, 2025). "These habits are associated with a lower risk of cardiovascular disease, improved insulin sensitivity, decreased risk of certain types of cancer, and positive effects on cognition, in addition to being considered as one of the world diets for the prevention and treatment of type 2 diabetes." (PMID 41567333, 2025). "The study found that PAHs were associated with type 2 diabetes mellitus (T2DM) for reasons including inflammation of active, resistant insulin, change in cytokine release, oxidative stress, and interference of the endocrine system." (PMID 41158558, 2025). "Additionally, they demonstrated more efficient lipid utilization during PA, characterized by reduced diacylglycerol levels, which could enhance insulin sensitivity and lower the risk of type 2 diabetes." (PMID 40066156, 2025). "Several enriched pathways, such as Type II diabetes mellitus, Integration of energy metabolism, and Peptide hormone metabolism, are associated with the hallmark of deregulated nutrient sensing, which encompasses insulin/IGF-1 signaling and metabolic dysregulation in aging." (PMID 40585135, 2025). "Moreover, alterations in the insulin signaling pathway, a hallmark of type 2 diabetes, were associated with the aggressive behavior of UCEC, suggesting that therapeutic interventions targeting this pathway may be particularly important for diabetic patients." (PMID 41244925, 2025). "Among the various forms of this disease, type 2 diabetes mellitus (T2DM), distinguished by the gradual loss of pancreatic β-cell function in conjunction with reduced tissue sensitivity to insulin, remains the most widespread and burdensome." (PMID 41154693, 2025). "Type 2 diabetes mellitus (T2DM) is a complex metabolic disorder marked by consistently high blood sugar levels, primarily caused by insulin resistance and impaired function of pancreatic β-cells." (PMID 40733260, 2025). "Sulfonylureas are ubiquitously employed as antidiabetic drugs for type 2 diabetes mellitus (T2DM) with characteristics of the deficiency of insulin secretion and/or insulin resistance (IR), a metabolic illness afflicting millions of people worldwide." (PMID 40625684, 2025). "Among Caucasian populations, the Ala variant has been initially associated with lower body mass index (BMI) and improved insulin sensitivity, especially in individuals with obesity or type 2 diabetes (T2D)." (PMID 41300761, 2025). "Similarly, the environmental factor is one of the primary modulators of the risk and progression of type 2 diabetes, where the presence of an obesogenic environment—characterized by excessive accumulation of visceral adipose tissue—exacerbates insulin resistance." (PMID 40076782, 2025).
type 2 diabetes (continued). "Reduced Akkermansia muciniphila levels, for example, have been linked to impaired insulin secretion in individuals with newly diagnosed type 2 diabetes (T2DM)​." (PMID 40742490, 2025). "In our study, we demonstrated that switching from premixed biphase insulin treatment to a combination of iDegLira for six months may improve glycemic control, reduce insulin requirements, and promote weight loss in patients with type 2 diabetes, while maintaining low glycemic variability." (PMID 41268167, 2025). "Type 2 diabetes mellitus (T2DM) is a chronic disease characterized by hyperglycemia, usually due to insulin resistance and progressive loss of insulin secretion or function from the pancreatic β-cells." (PMID 41316005, 2025). "Type 2 diabetes mellitus (T2DM) develops owing to a combination of genetically predisposed reduction in insulin secretion and insulin resistance caused by environmental factors such as high-calorie diets, high-fat intake, and physical inactivity." (PMID 40741556, 2025). "Type 2 diabetes mellitus (T2DM) is a common chronic metabolic disease, mainly caused by the combined effect of insulin resistance and insufficient insulin secretion, resulting in elevated blood sugar levels in the body." (PMID 41585785, 2025). "Muscles produce myokines released during physical activity, which support glucose metabolism by enhancing insulin sensitivity and additionally exert anti-inflammatory effects, inhibit lipid accumulation, and counteract sarcopenia progression, thereby reducing the risk of type 2 diabetes." (PMID 40944248, 2025). "The development and progression of type 2 diabetes are usually associated with obesity, especially with excess visceral fat, which triggers many events such as cytokine imbalance, chronic inflammation or susceptibility to oxidative stress, affecting insulin signaling and glucose or lipid metabolism." (PMID 40904859, 2025). "Moreover, it remains unclear how daily life stress is related to peripheral glucose levels in participants that have increased insulin levels and are at risk of developing type 2 diabetes." (PMID 41076451, 2025). "In individuals with type 2 diabetes mellitus T2DM, a condition marked by hyperglycemia and impaired insulin secretion, vitamin D deficiency is associated with increased risk of both microvascular and macrovascular complications." (PMID 40943440, 2025). "While olive oil, particularly extra virgin olive oil (EVOO), has been widely recognized for its health benefits, including its positive effects on type 2 diabetes (T2DM) risk and insulin sensitivity, several limitations in current research must be addressed." (PMID 39940428, 2025). "These self-reinforcing cycles between the liver and pancreas may finally cause a reduction in pancreatic insulin secretion after meals and the onset of hyperglycemia in susceptible individuals, suggesting that type 2 diabetes is (mainly) caused by excess fat inside the liver and the pancreas." (PMID 38791525, 2024). "Additionally, we found a beneficial association between EGP with plasma LDL-C, suggesting LDL-C might decrease EGP and thus improve hepatic insulin sensitivity and potentially and paradoxically reduce the risk of type 2 diabetes." (PMID 38989003, 2024). "Moreover, the onset of PD has been linked to type 2 diabetes and desensitized insulin signaling." (PMID 38921025, 2024). "However, a consensus is emerging that estrogen replacement may be beneficial for β-cell insulin secretion, glucose effectiveness, and insulin sensitivity, decreasing the risk of type 2 diabetes." (PMID 38883397, 2024). "Type 1 and type 2 diabetes mellitus (T2DM) are lifestyle-related diseases characterized by high blood sugar levels due to an absolute or relative deficiency of the hormone insulin." (PMID 39310505, 2024). "Additionally, experimental studies have suggested that PTEN mutations may reduce the risk of type 2 diabetes by enhancing insulin sensitivity." (PMID 39682196, 2024).
type 2 diabetes (continued). "Additionally, VK may lower the risk of metabolic disorders such as type 2 diabetes by enhancing insulin sensitivity and exerting anti-inflammatory effects [122, 123}." (PMID 39770962, 2024). "Furthermore, dragon fruit’s ability to improve insulin sensitivity may help mitigate the risk of type 2 diabetes, which is often associated with dyslipidemia and obesity." (PMID 39683835, 2024). "Nevertheless, glucose and insulin responses were blunted after acute and repeated consumption of S&SE reformulated biscuits, which may confer a benefit for blood glucose control, for example in individuals at risk of developing type 2 diabetes." (PMID 38553262, 2024). "Additionally, the beneficial association between EGP and plasma LDL-C, suggests that LDL-C may decrease EGP and thus improve hepatic insulin sensitivity and paradoxically reduce the risk of type 2 diabetes." (PMID 38989003, 2024). "Compared to previous groups of adult-onset diabetes, this group of individuals had the greatest familial risk score for type 2 diabetes, the lowest level of metabolic control throughout time, a faster development towards continuous insulin use, and a greater likelihood of diabetic retinopathy." (PMID 38654804, 2024). "Type 2 diabetes mellitus (T2DM) is a chronic metabolic disorder characterized by a combination of insulin resistance (IR) and a decline in insulin production due to loss of pancreatic β-cells." (PMID 39684879, 2024). "However, recently reported findings demonstrated thatdocosahexaenoic (DHA) and arachidonic acids (ARA), ω-3 and ω-6LCPUFAs, accelerated the aggregation rates of insulin and α-synuclein,proteins that are directly linked to diabetes type 2 and Parkinson’sdisease, respectively." (PMID 38127718, 2024). "Type 2 diabetes (T2DM) is the progressive loss of insulin secretion from β-cells in the context of insulin resistance, which is commonly complicated with MASLD." (PMID 38971765, 2024). "Type 2 diabetes mellitus (T2DM) is a chronic condition with high blood sugar levels caused by insulin resistance and/or inadequate insulin production." (PMID 39429814, 2024). "Moreover, the improvement in hepatic insulin sensitivity observed in patients with type 2 diabetes following weight loss is also accompanied by a significant reduction in intrahepatic fat without any changes in circulating adipocytokines (interleukin-6, resistin, leptin)." (PMID 38791525, 2024). "Impaired insulin secretory capacity is associated with high glycemic variability in patients with type 2 diabetes (T2DM)." (PMID 38839813, 2024). "Type 2 diabetes mellitus (T2DM) is a disease characterized by high blood sugar symptoms caused by islet dysfunction and cell resistance to insulin." (PMID 39872318, 2024). "Elevated serum levels of imidazole propionate are associated with the development of type 2 diabetes, and, since UrdA is only present in humans in gut bacteria, this enzyme has emerged as a significant factor linking the health of the gut microbiome and insulin resistance." (PMID 38280427, 2024). "In human subjects, low ghrelin plasma concentration were associated with circulating insulin concentrations, hypertension, and type 2 diabetes mellitus (T2DM)." (PMID 39070294, 2024). "In the early stages, pancreatic β-cells could compensate by increasing insulin secretion to offset the deficiency; however, over time, their function gradually deteriorated, leading to impaired glucose tolerance, prediabetes, and the onset of type 2 diabetes." (PMID 39737158, 2024). "Type 2 diabetes mellitus (T2DM) is a severe global disease characterized by hyperglycemia caused by gradually losing the ability to produce enough insulin associated with insulin resistance." (PMID 39415289, 2024). "Accordingly, for over a century, a link between insulin sensitivity and resistance (IR), a typical hallmark of type 2 diabetes mellitus (T2DM), and HF has been noted." (PMID 37679763, 2023).
type 2 diabetes (continued). "Methylation presence has been identified among women with preeclampsia, and in cord blood, which could decrease the numbers of stem cells involved in islet cell development, with an increased risk for abnormal insulin secretion, resistance to insulin, and type 2 diabetes in offspring." (PMID 36797785, 2023). "Therefore, we suggest that clinicians should consider that patients with cancer may have a higher risk of developing type 2 diabetes and require insulin treatment." (PMID 36831436, 2023). "Therefore, it provides a target for the design of inhibitors that might enable β-cell regeneration, thus contributing to reducing insulin-producing cell loss in type I diabetes and increasing their efficiency in type II diabetes." (PMID 37195917, 2023). "Furthermore, improvements in insulin signalling conferred by LC/KD (as evident in treatment of obesity and type 2 diabetes) may be associated with mood benefits." (PMID 37066662, 2023). "Reduced levels of HDL-C are often present in resistance to insulin, obesity and type 2 diabetes mellitus (T2DM) and are associated with hypertension and dyslipidemia, factors that can lead to the early development of CAD." (PMID 36651718, 2023). "Moreover, our study suggests that sleep apnea may predispose to an early onset of prediabetes and type 2 diabetes by impairing early insulin secretion in children and adolescents with obesity." (PMID 36670156, 2023). "Once-daily insulin degludec is another albumin-bound insulin and was shown in double-blind crossover Phase 3 trials to be associated with a reduced rate of overall symptomatic hypoglycaemia during 32 weeks of treatment as compared with once-daily glargine U100 in both type 1 and type 2 diabetes." (PMID 37308751, 2023). "NAFLD and the cornerstones of metabolic syndrome (type 2 diabetes mellitus—T2DM, visceral obesity, arterial hypertension, dyslipidemia) share a common pathogenesis, closely linked to resistance to insulin action." (PMID 36675217, 2023). "While genetic variants such as TBC1D4 and TCF7L2 result in up to 50% increased risk of type 2 diabetes by diminishing the incretin effect and impairing glucagon-like peptide 1–induced insulin secretion, a fiber-rich diet may stimulate glucagon-like peptide 1 and mitigate this genetic risk." (PMID 38049803, 2023). "Type 2 diabetes mellitus (T2DM) is caused by the inefficient use of insulin by the body and in more than 95% of cases is largely due to obesity and lack of physical exercise." (PMID 36769502, 2023). "The most common metabolic disorder, type 2 diabetes mellitus (T2D) is characterized by chronic hyperglycemia that is caused by insulin resistance and/or deficient insulin release." (PMID 37175953, 2023). "Low doses (20 μg/kg) and diminished exposure to NDEA have been shown to cause type 2 diabetes mellitus (T2DM), cognitive impairments, and Alzheimer’s disease (AD)-type neurodegeneration with peripheral and cerebral insulin resistance in animal models." (PMID 37759689, 2023). "Due to the considerable glucose demand of skeletal muscles, alterations in the complex mechanisms that regulate insulin-dependent glucose uptake and skeletal muscle metabolism may impact glucose homeostasis and predispose individuals to type 2 diabetes (T2D) development." (PMID 37210436, 2023). "Little evidence exists, however, of analysis regarding the association between IA subclasses and glycemic control in insulin-treated patients with type 2 diabetes (T2D)." (PMID 37143729, 2023). "Type 2 diabetes mellitus (T2DM) has become a serious health concern in developing countries, and is caused by insulin resistance due to altered β-insulin secretion or deficiency." (PMID 36613397, 2023).